EFNB3 (ephrin B3)
Description:
Cell surface transmembrane ligand for Eph receptors, a family of receptor tyrosine kinases which are crucial for migration, repulsion and adhesion during neuronal, vascular and epithelial development. Binds promiscuously Eph receptors residing on adjacent cells, leading to contact-dependent bidirectional signaling into neighboring cells. The signaling pathway downstream of the receptor is referred to as forward signaling while the signaling pathway downstream of the ephrin ligand is referred to as reverse signaling. May play a pivotal role in forebrain function. Binds to, and induce the collapse of, commissural axons/growth cones in vitro. May play a role in constraining the orientation of longitudinally projecting axons (By similarity). (Microbial infection) Acts as a receptor for nipah virus and hendra virus.
Synonyms: LERK-8; EPLG8; LERK8; EFL6
Tractability: Antibody: its Gene Ontology location is reachable by antibodies, with high confidence; UniProt predicts a signal peptide or a membrane-spanning region. PROTAC: its protein half-life has been measured.
Gene: Protein-coding gene on chromosome 17 (7,705,202 to 7,711,372, forward strand). Ensembl gene ENSG00000108947.
Subcellular location: Membrane
Pathways (Reactome):
Developmental Biology: EPH-Ephrin signaling; EPH-ephrin mediated repulsion of cells; EPHB-mediated forward signaling; Ephrin signaling
Gene Ontology:
Molecular function: ephrin receptor binding; protein binding; transmembrane-ephrin receptor activity
Biological process: ephrin receptor signaling pathway; axon guidance; cell-cell signaling; negative regulation of axonogenesis; nervous system development; trans-synaptic signaling by trans-synaptic complex, modulating synaptic transmission
Cellular component: plasma membrane; glutamatergic synapse; presynaptic membrane; hippocampal mossy fiber to CA3 synapse; membrane
Genetic constraint (gnomAD): Loss-of-function variants: 13 observed, 25.66 expected, observed/expected ratio (o/e) 0.51, 90% interval 0.33 to 0.81. The upper end of that interval is the gene's LOEUF score, 0.81, which puts it in group 3 of 6, group 1 being the genes least tolerant of losing a copy. Missense variants: 388 observed, 411.64 expected, observed/expected ratio (o/e) 0.94, 90% interval 0.87 to 1.02. Synonymous variants: 203 observed, 173.81 expected, observed/expected ratio (o/e) 1.17, 90% interval 1.04 to 1.31.
Homologues: Orthologues: chimpanzee EFNB3 (99% identical), macaque EFNB3 (99% identical), rabbit EFNB3 (99% identical), dog EFNB3 (97% identical), pig EFNB3 (97% identical), guinea pig EFNB3 (96% identical), mouse Efnb3 (96% identical), tropical clawed frog efnb3 (56% identical), zebrafish efnb3b (55% identical), zebrafish efnb3a (49% identical), Drosophila melanogaster Ephrin (24% identical), Caenorhabditis elegans vab-2 (19% identical), and 3 more. Paralogues in human: EFNB1 (40% identical), EFNB2 (39% identical), EFNA3 (16% identical), EFNA2 (15% identical), EFNA5 (15% identical), EFNA1 (13% identical), EFNA4 (12% identical).
Diseases named in the same sentence as EFNB3 in open-access papers:
EFNB3 is named in the same sentence as 39 diseases in open-access papers, as found by Europe PMC text mining. Sharing a sentence is not in itself a finding about the gene and the disease. The quoted sentences say what the papers report.
glioma (7 papers, 2014 to 2024). A benign or malignant brain and spinal cord tumor that arises from glial cells (astrocytes, oligodendrocytes, ependymal cells). "Namely, EPHA2 expression in osteosarcoma has been correlated with invasive capacity and increased ephrin-B3 in glioma with more aggressive behavior." (PMID 38612645, 2024). "Ephrin-B3 has also been reported to characterize a glioma-aggressive phenotype, promoting invasion via Rac1 activation." (PMID 38612645, 2024). "Forced overexpression of Ephrin B3 was similarly reported to increase invasion of glioma cells in vitro via a pathway involving Rac." (PMID 27533087, 2016). "First, miR‐204 targets EphB2 in glioma cells and regulates retinal axon guidance through Efnb3 (ephrin ligand) and EphB2 (receptor) during eye development in medaka." (PMID 26799631, 2016). "Similarly, EphB2, by interacting with either ephrin-B1 or ephrin-B3, stimulates invasion in glioma cells." (PMID 34360867, 2021). "Ephrin-B3 expression level was moderate (n = 1) to high (n = 4) in more than 70% of glioblastoma samples, whereas its expression is rather low in all low-grade glioma tested." (PMID 28423606, 2017). "Thus EphA2 localization in breast cancer cells has been found to be controlled by E-cadherin and Ephrin B3 was reported to influence EMT via the small GTPase Rac in glioma cells." (PMID 27533087, 2016). "Specifically, the observation that a high expression of EPHA2 in neuroblastoma, EPHB1 in glioma, EPHB6, ephrin-B2, and ephrin-B3 in neuroblastoma correlates with a better prognosis is in line with a tumor-suppressive role of these EPHs." (PMID 38612645, 2024). "On the other hand, high expression levels of EPHA2 in neuroblastoma, of EPHB1 in glioma, and of EPHB6, ephrin-B2 and ephrin-B3 in neuroblastoma confer a better prognosis." (PMID 38612645, 2024). "We analysed Ephrin-B3 expression at the protein level by immunohistochemistry, on 7 glioblastoma WHO grade IV and 3 glioma WHO grade II–II (one oligodendroglioma grade II, one astrocytoma grade II and one astrocytoma grade III)." (PMID 28423606, 2017). "Moreover, in glioma cells Ephrin B3 was shown to interact with the EMT signaling component Rac and in this way control its activation and glioma cell invasion capacity." (PMID 27533087, 2016). "Cell contact-mediated bidirectional EFNB3/EPHA4 signaling and migration of interneurons during cerebral cortex development has been previously reported, suggesting the possible usage of this interaction during glioma invasion." (PMID 25365423, 2014). "In addition, a potential cell-cell interaction between Efnb3 expressing cells at the microenvironment and EPHA4 expressing glioma cells at the AOI was suggested." (PMID 25365423, 2014).
Hypertension (5 papers, 2016 to 2022). The presence of chronic increased pressure in the systemic arterial system. "The results show that the one SNP in the 5′ end upstream of the EFNB3 gene start site was significantly associated with hypertension risks." (PMID 30262919, 2018). "This is consistent with the results of our current human genetic study, in which we reveal that three EFNB3 SNPs are significantly associated with hypertension in hypogonadic patients." (PMID 30262919, 2018). "Our genetic investigation in patients recruited from the ADVANCE study revealed significant association of 2 SNPs within the EFNB3 gene with hypertension in T2D patients." (PMID 28272517, 2017). "In summary, in this study, we discovered a significant association of 2 SNPs in the EFNB3 gene with hypertension in a human genetic study." (PMID 28272517, 2017). "The results reveal that 2 SNPs in the EFNB3 gene were significant for their association with hypertension in T2D patients." (PMID 28272517, 2017). "It is possible that some of these hypogonadic hypertension patients suffer from EFNB3 mutations, and the concerted effect of lower testosterone levels and EFNB3 mutation renders them prone to hypertension, as is the case in castrated Efnb3 KO mice." (PMID 28272517, 2017). "Recently, the ephrin-B3 gene (EFNB3) has been suggested to be a hypertension risk gene in certain individuals." (PMID 29208002, 2017). "To prove experimentally that EFNB3 mutations in the hypogonadic patients could indeed cause hypertension, we investigated the BP in EFNB3 KO mice." (PMID 30262919, 2018). "To assess whether this finding in mice is relevant to human hypertension, we conducted a human genetic study for the association of EPHB6 and its two ligands, EFNB1 and EFNB3, with hypertension in hypogonadic patients." (PMID 30262919, 2018). "However, in male T2D patients, 2 EFNB3 SNPs (rs7141 and rs3744263) were significantly and positively associated with hypertension." (PMID 28272517, 2017). "Hence, the ADVANCE cohort provides us with a unique situation to reveal the association of the EFNB3 SNPs with hypertension in these male T2D patients." (PMID 28272517, 2017). "Thus, our investigation has shown that EFNB3 is a hypertension risk gene in certain individuals." (PMID 28272517, 2017). "For example, female hypertensive patients with EFNB3 mutations could be identified by genetic testing, and for this subpopulation of patients, avoidance of oral contraceptive/hormone replacement could reduce their hypertension risks." (PMID 27941904, 2016). "To assess the relevance of this phenotype to human hypertension, in this study we investigated the association of SNPs in the EPHB6 gene, and in the genes of its two ligands, EFNB1 and EFNB3, with hypertension in Han Chinese hypogonadic males." (PMID 30262919, 2018). "Previous animal studies showed that while male EFNB3 gene knockout mice were normotensive, castration of these mice resulted in hypertension, corroborating the results of the human genetic study." (PMID 30262919, 2018). "The deletion of EPHB6, EFNB1 and EFNB3 all result in hypertension in mice, while the deletion of EFNB2 leads to an opposite phenotype, i. e., hypotension." (PMID 30262919, 2018). "We have observed significant association between 2 SNPs in the 3′ untranslated region or within the adjacent region just 3′ of the EFNB3 gene with hypertension, corroborating our findings from the mouse model." (PMID 28272517, 2017). "For seven of overall 17 potential target genes, we found studies reporting a role in CVD, comprising HF and cardiac remodeling after MI (Ccnd2, Pde1c, Ddah1), atherosclerosis (Igf1r), blood pressure and hypertension (Fign, Efnb3), and type 2 diabetes (Igf2bp2)." (PMID 35332188, 2022). "As a consequence, compared to individuals without such EFNB3 loss-of-function mutations, these patients will have relatively increased hypertension risks." (PMID 30262919, 2018).
Hypertension (continued). "Why were SNPs in the EFNB3 gene but not the EPHB6 gene significantly associated with hypertension in hypogonadic males, in spite of the EPHB6 KO leading to hypertension in castrated mice?" (PMID 30262919, 2018). "In the same cohort, two SNPs in the 3′ region of EFNB3 gene are associated with hypertension risks in male but not female Caucasians29." (PMID 30262919, 2018). "Why can we detect the association of 2 EFNB3 SNPs with hypertension in the ADVANCE study but none in the IBPC dataset?" (PMID 28272517, 2017). "Thus, we speculated that EFNB1 and EFNB3 are more relevant to EPHB6 signalling for the hypertension phenotype, and hence they were included in our current hypertension association study." (PMID 30262919, 2018). "In mice, Efnb3 KO males were normotensive and they only became hypertensive after castration, indicating that testosterone in the absence of EFNB3 is protective against hypertension." (PMID 28272517, 2017). "We recently reported that Efnb3 gene deletion results in hypertension in female but not male mice." (PMID 28272517, 2017).
autism (3 papers, 2011 to 2024). Persistent deficits in social interaction and communication and interaction as well as a markedly restricted repertoire of activity and interest as well as repetitive patterns of behavior. "In the literature, Ephrin-B3 is reported to be involved in regulation of innate emotional responses and fear accompanying the development of early emotional circuit disruptions in individuals with autism and schizophrenia." (PMID 39640846, 2024). "Real-time RT-PCR revealed that the relative expression levels of EFNB3, PLXNA4A and ROBO2, compared, with all three housekeeping genes were significantly lower in the ACC of people with autism than in the ACC of controls." (PMID 21859478, 2011).
neuroblastoma (3 papers, 2014 to 2024). Neuroblastoma (NB) is the most common solid, extracranial childhood tumor. "In their first study, they identified the expression of EPHB6, ephrin-B2, and ephrin-B3 in neuroblastoma cells, correlating with a favorable prognosis." (PMID 38612645, 2024). "While Pea3 upregulates transcription of Sema3D and represses Sema5B, for example, Erm and Er81 upregulate Sema5A and Er81 regulates Unc5C and Sema4G while repressing EFNB3 in SH-SY5Y neuroblastoma cells." (PMID 33097800, 2020). "Among the favorable neuroblastoma genes examined (EPHB6, EFNB2, EFNB3, TrkA, CD44, MIZ-1), S(+)-ibuprofen augmented the expression of EPHB6 significantly in four of five neuroblastoma cell lines tested." (PMID 24173829, 2014).
behavioral disorders (2 papers, 2015 to 2025). "Notably, genes associated with immune modulation and inflammation (e.g., Dusp1, Lrrc39, E2f2), neuroplasticity and memory (e.g., Cpeb3, Efnb3), and behavioral disorders (e.g., Pla2g4c) exhibited substantial changes." (PMID 40285614, 2025). "Finally, many genes associated with neurological development and behavioural disorders were pinpointed (CACNG2, CALN1, ACCN3, EFNB3, DLGAP1 and ATP1B2)." (PMID 26100250, 2015).
encephalitis (2 papers, 2024). An acute inflammatory process affecting the brain parenchyma. "EFNB2 is likely the key receptor for Nipah virus for transmission, while EFNB3-mediated infection may contribute to the fatal encephalitis and brain pathology frequently observed in human infections." (PMID 38659959, 2024).
glioblastoma (2 papers, 2017 to 2025). The most malignant astrocytic tumor (WHO grade IV). "In patient tumors, ephrin-B3 expression and phosphorylation levels correlate with histological grade and are enriched in invasive glioblastoma cells." (PMID 41200151, 2025). "The pair EphA4/Ephrin-B3 favors survival of neuronal progenitors of the brain subventricular zone, an area where glioblastoma multiform (GBM) are thought to originate." (PMID 28423606, 2017). "Ephrin-B3 via its ability to block EphA4-induced apoptosis is likely involved in glioblastoma tumorigenesis, since its specific invalidation is sufficient to slow down tumor growth in a xenograft model." (PMID 28423606, 2017). "Along this line, Ephrin-B3 was described as highly expressed in glioblastoma biopsies and notably in invasive tumoral cells." (PMID 28423606, 2017). "We show here that Ephrin-B3 behaves as a survival factor for glioblastoma bulk by acting notably on endothelial cells." (PMID 28423606, 2017). "We then aimed to determine whether high expression level of Ephrin-B3 in glioblastoma biopsies could represent a selective advantage for tumoral cells." (PMID 28423606, 2017).
hypogonadic (2 papers, 2017 to 2018). "Therefore, it is conceivable that more than 30% of the male patients in the ADVANCE study suffer from hypogonadism, reminiscent of the reduced testosterone levels in the castrated Efnb3 KO males." (PMID 28272517, 2017).
viral infections (2 papers, 2016 to 2025). "EFNB1 and its homologs EFNB2 and EFNB3 have previously been implicated in viral infections as receptors for henipaviruses, including Nipah, Hendra and Cedar viruses." (PMID 41332748, 2025).
age-related macular degeneration (1 paper, 2021). Age-related loss of vision in the central portion of the retina (macula), secondary to retinal degeneration. "WEE1, SMC2, HMGB1, RRM2, and POLA1 proteins were also observed to be involved in the progression and invasion of retinoblastoma; SLC24A2 and DTX4 in age-related macular degeneration; and EPHB6, EFNB3, and SHC1 in glaucoma." (PMID 34646884, 2021).
brain injury (1 paper, 2025). Acute and chronic (see also brain INJURIES, CHRONIC) injuries to the brain, including the cerebral hemispheres, CEREBELLUM, and brain STEM. "Previous studies have shown that EFNB3 negatively regulates endogenous neurogenesis in the adult CNS, while cell proliferation in the SVZ regions is significantly enhanced in EFNB3 knockout mice after ischimic brain injury." (PMID 41164797, 2025).
experimental autoimmune encephalomyelitis (1 paper, 2022). An autoimmune demyelinating disease of the central nervous system that is produced experimentally in animals by the injection of homogenized brain or spinal cord in Freund's adjuvant. "Interestingly, increased microglial expression of Efnb3 was recently demonstrated in experimental autoimmune encephalomyelitis (EAE)." (PMID 36153535, 2022).
Hyperglycemia (1 paper, 2017). An increased concentration of glucose in the blood. "Decreased expression of axon guidance pathway genes, Robo1, Ntn1, Ntng1, Nrp1, and Efnb3 in NSCs exposed to hyperglycemia was suggestive that miRNAs could target and deregulate the axonal guidance pathway as predicted by the pathway analysis." (PMID 28798665, 2017).
lung carcinoma (1 paper, 2013). "For example, ephrin-B3 knockdown revealed that this ephrin increases EphA2 expression in the U-1810 lung cancer cell line." (PMID 24348920, 2013).
melanoma (1 paper, 2016). A malignant, usually aggressive tumor composed of atypical, neoplastic melanocytes. "The Ephrin ligand EFNB3 was contained in a region of copy loss and EFNB3 mRNA expression was significantly decreased in metastatic compared to primary melanomas." (PMID 27095580, 2016).
small cell lung carcinoma (1 paper, 2021). Small cell lung cancer (SCLC) is a highly aggressive malignant neoplasm, accounting for 10-15% of lung cancer cases, characterized byrapid growth, and early metastasis. "EPHB2, as an EPHB subgroup receptor kinase, could modulate the biological behavior of small cell lung carcinoma through autocrine and/or juxtracrine activation by ephrin-B ligands (EFNB1, EFNB2, and EFNB3) that are expressed in the same or neighboring cells." (PMID 34645436, 2021).